CTH (cystathionine gamma-lyase)
Diseases named in the same sentence as CTH in open-access papers (continued):
Sharing a sentence is not in itself a finding about the gene and the disease.
tumor (continued). "In summary, our results indicated that the reduction of CTH expression in PC3 cells decreased tumor growth, as well as paraaortic lymph node and bone metastasis." (PMID 31468690, 2019). "Knockdown of CTH in PC3 cells results in the suppression of tumor growth and distant metastasis, while overexpression of CTH in DU145 cells promotes primary tumor growth and lymph node metastasis in the orthotopic implanted xenograft mouse model." (PMID 31468690, 2019). "Besides, we identified two genes, ADIPOQ and CTH, that exhibit a mixed pattern across tumor stages and ER/PR status." (PMID 40420636, 2026). "Moreover, tumor weights at endpoint were significantly lower in the shCTH group, confirming the tumor-suppressive effect of CTH knockdown." (PMID 41153607, 2025). "The enzymes involved in this pathway, including glycine N-methyltransferase (GNMT), S-adenosylhomocysteine hydrolase (SAHH), cystathionine β-synthase (CBS), and cystathionine gamma-lyase (CTH), sensitize cancer cells to ferroptosis and slow down tumor progression." (PMID 41323780, 2025). "Together, these findings indicate that CTH acts as a functional driver in DLBCL by promoting tumor cell proliferation and inhibiting apoptosis and may be a potential target for DLBCL therapy." (PMID 41153607, 2025). "Increased production of hydrogen sulfide (H2S) by CTH was at least partially responsible for tumor vascular normalization, leading to decreased leakiness and enhanced delivery of chemotherapeutic agents to the tumor." (PMID 39163136, 2024). "Notably, CTH-mediated production of H2S reduces tumor growth and GSC abundance, while cysteine production enables peroxide-dependent brain invasion." (PMID 38299594, 2024). "In this study, we hypothesized that inhibiting CTH in the tumor microenvironment could have potentially anti-tumoral effects since similar effects of CTH have been shown in other cancer types." (PMID 37300955, 2023). "In particular, the exact biological role of CTH expressed in the tumor stroma (microenvironment) vs the GBM tumor cells per se remains to a large extend unknown especially under the setting of immunocompetent mice." (PMID 37300955, 2023). "In order to identify the most important cell type(s) leading to lower tumoral SOX2 levels in the CTH KO, a series of tumor microenvironment cell-specific CTH KO mice would have to be created (i.e knockout in endothelial cells, macrophages, astrocytes) which was beyond the scope of the current study." (PMID 37300955, 2023). "A function of low CTH levels in resistant tumour cell lines remains to be elucidated, yet." (PMID 35084545, 2022). "Cancer cells express high levels of CBS and CTH and their genetic or pharmacological inhibition leads to a reduction in tumor vasculature, suggesting that the TSP metabolic reprogramming may be a promising therapeutic strategy for solid tumors." (PMID 35681715, 2022). "Therefore, it is highly possible that ERK1/2 activities, which can be stimulated by H2S-mediated persulfidation on MEK1, are the key drivers to promote tumor growth in CBS or CTH overexpressing tumors." (PMID 34207284, 2021). "In addition, promoter methylation of CTH gene was positively correlated with aggressive tumor behaviors." (PMID 33522955, 2021). "In conclusion, cancer cells under hypoxia may produce H2S through induction of CTH to facilitate angiogenesis and tumor growth." (PMID 34207284, 2021). "Also, it is evident that FO consumption has significantly induced the expression of xCT antiporter and CTH proteins in tumor tissues." (PMID 33137095, 2020). "Furthermore, fish oil consumption induced an increment of GSSG/GSH ratio, an upregulation of xCT and CTH proteins in tumor tissues." (PMID 33137095, 2020). "Increased expression of CTH in bone‐metastatic PC cells induced a change in H2S level, resulting in the activation of IL‐1β/NF‐κB‐mediated signaling to promote cell invasion, angiogenesis, lymphangiogenesis, tumor growth, and metastasis." (PMID 31468690, 2019).
tumor (continued). "Overall, our data suggested a novel mechanism whereby CTH/H2S may facilitate PC metastasis through enhancing lymphangiogenesis in the tumor microenvironment." (PMID 31468690, 2019). "Further investigation of the CTH gene in colorectal carcinogenesis with regards to KRAS and BRAF mutations or other molecular characteristics of the tumor may be warranted." (PMID 29694444, 2018). "This yielded 88 genes associated with tumor grade, in which seven DEGs (C8orf33, TSNAXIP1, TM4SF1, CTH, ANXA2, KIAA1522 and LRRC1) can distinguish HCC of G3 from G1, two DEGs (CYB5A and RRAGD) can distinguish HCC of G3 from G2, and two DEGs (CFHR4 and F13B) can distinguish HCC of G3 from G4." (PMID 29123978, 2017). "However, inhibiting CTH resulted in a larger overall tumor mass." (PMID 38299594, 2024). "Moreover, we hypothesized that direct CTH inhibition on mouse and human GBM cells could have extra anti-tumoral functions, aiding and supporting the anti-tumoral effect of CTH inhibition in the tumor stroma." (PMID 37300955, 2023). "In conclusion, we demonstrated that GRP78 S‐sulfhydration, mediated by the endogenous CTH‐H2S axis or exogenous H2S, can promote M1 macrophage polarization via activating the IRE‐1α‐ERS pathway, resulting in inhibition of tumor growth and metastasis in BC." (PMID 39755930, 2025). "For example, ARSG, CTH, PDK1, and PDK4 are heavily involved in cellular metabolism and oxidative stress regulation, pathways tightly coupled with tumor proliferation and survival under adverse microenvironmental conditions." (PMID 41153607, 2025). "The CTH/H2S pathway results in proliferation and migration of CRC cells, and growth of tumor xenografts in nude mice." (PMID 39427081, 2024). "When evaluating the role of CTH and its metabolites in GBM, spatial and functional assessment of gene expression within the tumor as well as stage of tumor growth should be considered." (PMID 38299594, 2024). "However, future studies are needed in order to elucidate if there are any differences in tumor macrophage subpopulations (i.e M1 and M2) or in the numbers of other immune cell types that infiltrate the tumor microenvironment, and whether CTH might be involved in such changes." (PMID 37300955, 2023). "mCTH-ANV refers to mutant cystathionine gamma-lyase fused to ANV, thereby targeting PS exposed to the tumor vascular system." (PMID 36835282, 2023). "Up-regulation of CTH significantly inhibited tumor growth induced by Huh7-FOXC1 cells, whereas down-regulated CTH rescued the decreased tumor growth mediated by FOXC1 knockdown by In vivo tumorigenicity assays." (PMID 33522955, 2021). "This outcome is also justified as consumption of FO induces an upregulation of xCT and CTH proteins and reduces the expression of CBS proteins in tumor tissues." (PMID 33137095, 2020). "The expression of CTH in primary tumors increased considerably in patients with advanced stages (III/IV), as compared with the adjacent non‐tumor tissue or early‐stage tumors (I/II)." (PMID 31468690, 2019). "In the CTH overexpressing group, the mouse weight was slightly decreased as compared to the control group (Fig EV5B), and tumor size was significantly increased in comparison with the control group (Fig EV5C and E)." (PMID 31468690, 2019). "Among them, CTH was further validated in our study as a functionally oncogenic gene; its knockdown significantly inhibited proliferation and induced apoptosis in DLBCL cells in vitro and suppressed tumor growth in vivo." (PMID 41153607, 2025). "Since elevated CTH promotes cancer metastasis, in our experiments, the reduced expression level of this enzyme may indicate that SAC counteracts tumor propagation." (PMID 38397425, 2024). "Interestingly, in KRASMut and WT tumor samples, a correlation was observed between CBS and CTH genes expression, corresponding to A549 and H292 genetic background, while the expression of CBS and CTH were not correlated in PC-9 cells (EGFRMut)." (PMID 38247476, 2023).
tumor (continued). "Our findings therefore suggest that the absence of CTH in the tumor microenvironment and not in the tumor per se, is sufficient for regulating tumoral SOX2 expression." (PMID 37300955, 2023). "CTH KO mice with GBM have significantly lower tumor volume, tumoral SOX2 expression and no alteration in the levels of tumoral vascular density compared to WT mice with GBM." (PMID 37300955, 2023). "Finally, and in order to clarify if direct CTH inhibition on the tumor cells could trigger any additional anti-tumoral effects, human and mouse GBM cells were treated with pharmacological (PAG) or molecular (siRNA) CTH inhibitors." (PMID 37300955, 2023). "Whether CTH inhibition in the tumor cells per se but not in the stroma, could have an effect on angiogenesis, remains to be elucidated." (PMID 37300955, 2023). "Interestingly, bio-informatic analysis performed by us in the current study revealed a positive and significant correlation between CTH and SOX2 mRNA expression in human GBM tumors but whether this correlation is driven by the tumor microenvironment, or the tumor cells alone remained unknown." (PMID 37300955, 2023).
cancer (29 papers, 2014 to 2025). A tumor composed of atypical neoplastic, often pleomorphic cells that invade other tissues. "The involvement of mutations in the CTH gene has been proposed in several types of cancer, but their precise contribution to the formation of GBM is still not well understood." (PMID 38933650, 2024). "The CTH/H2S system plays a part in both health and diseases, and is implicated in the regulation of multiple physiological and pathological effects, including inflammation, immune response, cell differentiation, cancer, aging and the injury process." (PMID 36233122, 2022). "The CTH/H2S system plays a part in both health and diseases, and CTH-derived H2S is implicated in the regulation of multiple signal physiological effects, including immune response, cell differentiation, cancer, aging and the injury process." (PMID 36233122, 2022). "CTH breaks down cystathionine into cysteine, and deficiencies in CTH activity have also been shown to contribute to glutathione depletion in patients with cancer." (PMID 32701483, 2020). "Considering the correlation between CXCL5 and CTH expression and its association with the metabolism regulation and cancer progression, CXCL5-CTH axis may orchestrates the overall metabolic programming and 3D cancer progression, which warrants further investigation." (PMID 40050422, 2025). "In a previous study, CTH (CCC) was found to be of potential clinical importance for CCC carcinomas in EOC specifically with its capability of stratifying CCC and HGSC." (PMID 40778374, 2025). "Different types of cancer, including prostate cancer, gastric cancer, and melanoma cells, exhibit an increase in CTH." (PMID 38933650, 2024). "The expressions of xCT were higher in cancer cells than in normal cells, whereas the expressions of enzymes responsible for de novo cysteine synthesis, cystathionine-β-synthase (CBS), and cystathionine-γ-lyase (CTH), were lower in cancer cells than in healthy hepatocytes." (PMID 39413876, 2024). "Moreover, CTH can promote tumorigenesis via supporting angiogenesis mechanisms in other cancer types such as breast or prostate cancer." (PMID 37300955, 2023). "Importantly, we showed for the first time that the impact of PTGR2 on cancer cell death seemed to be the resultant of a defective antioxidative defense system involving xCT and CTH, both of which are important regulators of intracellular reduced GSH." (PMID 26820738, 2016). "In recent years, our research investigations have focused on the presence and role of enzymes (MPST, CTH, CBS) involved in the metabolism of low-molecular-weight sulfur compounds and H2S in normal and/or cancer cells." (PMID 38397425, 2024). "Hydrogen sulfide is also produced through cystathionine beta-synthase and cystathionine gamma-lyase, along with 3-MST, and is known to alleviate a variety of illnesses such as cancer, heart disease, and neurological conditions." (PMID 36978851, 2023). "Of the top down-regulated genes, PLAGL1, CTH and VIM are positively correlated with HNSCC, while increased expression of RMRP, SULT1 and LTBP1 has been recorded in other cancers." (PMID 31827722, 2019). "Cancer cells, which are treated with H2S donor, NaHS, and cancer cells, which recover from damage, show an increased CBS and CTH driven H2S synthesis, and increased Nampt, the rate-limiting factor in NAD+ biosynthesis, and its product NAD+." (PMID 25248148, 2014). "As compared to parental undamaged Pc cells, cancer cells recovered from damage had increased CBS and CTH proteins in direct correlation with the recovery period." (PMID 25248148, 2014).
cancer (continued). "Perhaps of greatest interest is understanding how this study adds to the growing body of literature that implicates the TSS pathway and its functional enzymes (i.e., CTH and CBS) as well as the metabolites utilized and produced by this pathway in GBM and in the broader field of cancer biology." (PMID 38299594, 2024).
infection (5 papers, 2020 to 2025). The state of being infected such as from the introduction of a foreign agent such as serum, vaccine, antigenic substance or organism. "In contrast, subtle defects in donor cells may not have a big impact on their capacity to fight infection, if the response has been properly orchestrated (notice that CTH-deficient murine neutrophils showed no defect in fungal killing)." (PMID 34061822, 2021). "Moreover, we also found a tendency of CTh to correlate positively with time since infection, potentially indicating patients with a higher time between infection and assessment may have worse structural changes as they have been carrying this PCC longer time with no recovery." (PMID 40008326, 2025). "Specifically, the expression of cystathionine gamma-lyase (CTH), which related to the synthesis of thiocysteine from cystine, was up-regulated after HIRRV infection." (PMID 37711614, 2023). "We found that DDIT4, CTH, RELB, and SLC7A11, but not NDRG1 and CHAC1, increased in gastric tissues at 4 months post-infection (MPI)." (PMID 32457731, 2020).
cardiovascular disease (3 papers, 2012 to 2022). "Previous studies have found that disorders of cystathionine-gamma-lyase/hydrogen sulfide (CSE/H2S) system in maintenance hemodialysis patients are correlated with the risk of cardiovascular disease." (PMID 33644113, 2020). "Hydrogen sulfide (H2S) is a gasotransmitter that is endogenously produced in the cardiovascular system by cystathionine gamma-lyase (CSE), which has shown great potential in treating cardiovascular diseases (CVDs)." (PMID 36588697, 2022).
cardiac diseases (2 papers, 2023). "This study is the first to investigate LUAD patients specifically, as prior research has primarily examined the impact of CTH polymorphism on the development and progress of cardiac diseases." (PMID 38107574, 2023).
hematological diseases (1 paper, 2016). "Compared with 9, the levels of oxLDL-IgG antibodies titer significantly increased, and the oxLDL-IgM titer decreased, and except 6, plasma CTH levels significant decline in the subsets (from 1 to 7) of the hematological diseases group (P < 0.001)." (PMID 27825356, 2016).
CTH also shares sentences with these, for which no sentence is quoted: diabetes (2 papers); endometrioid carcinoma (2); ischemia reperfusion injury (2); pancreatic adenocarcinoma (2); aneurysm (1); bladder cancer (1); brain cancer (1); chronic myeloid leukemia (1); colon cancer (1); diabetes insipidus (1); Down syndrome (1); endometrial cancer (1); endometrioid tumor (1); endothelial dysfunction (1); Fabry disease (1); hippocampal atrophy (1); homocystinuria (1); hyperlipidemia (1); hyperthyroidism (1); hypothyroidism (1); inherited diseases (1); iron deficiency (1); ischemia (1); liver (1); malaria (1); metabolic disorder (1); metastatic prostate carcinoma (1); myocardial infarction (1); nonalcoholic steatohepatitis (1); ovarian tumor (1).
A further 8 diseases each share a sentence with CTH in 1 paper.